SLC51A (solute carrier family 51 member A)
Description:
Essential component of the OST-alpha/OST-beta complex, a heterotetramer that acts as the intestinal basolateral transporter responsible for bile acid export from enterocytes into portal blood. The OST-alpha/OST-beta complex efficiently transports the major species of bile acids (taurocholate). Taurine conjugates are transported more efficiently across the basolateral membrane than glycine-conjugated bile acids (By similarity). In the complex, SLC51A/OST-alpha adopts a G protein-coupled receptor fold and constitutes a bile acid recognition site. Can also transport steroids such as estrone 3-sulfate and dehydroepiandrosterone 3-sulfate, therefore playing a role in the enterohepatic circulation of sterols. Able to transport eicosanoids such as prostaglandin E2 (By similarity).
Synonyms: OSTA; OSTalpha; SLC51A1; PFIC6
Tractability: Antibody: UniProt places it where antibodies can reach, with high confidence; its Gene Ontology location is reachable by antibodies, with high confidence; UniProt predicts a signal peptide or a membrane-spanning region. PROTAC: its protein half-life has been measured.
Target class: Transporter; SLC51 family of steroid-derived molecule transporters; SLC superfamily of solute carriers; Electrochemical transporter
Gene: Protein-coding gene on chromosome 3 (196,211,487 to 196,243,178, forward strand). Ensembl gene ENSG00000163959.
Subcellular location: Basolateral cell membrane
Pathways (Reactome):
Metabolism: Recycling of bile acids and salts
Gene Ontology:
Molecular function: bile acid transmembrane transporter activity; protein binding; transmembrane transporter activity; protein heterodimerization activity; protein homodimerization activity
Biological process: bile acid secretion; bile acid and bile salt transport; transmembrane transport
Cellular component: basolateral plasma membrane; plasma membrane; endoplasmic reticulum membrane; membrane; protein-containing complex
Genetic constraint (gnomAD): Loss-of-function variants: 24 observed, 36.53 expected, observed/expected ratio (o/e) 0.66, 90% interval 0.47 to 0.92. The upper end of that interval is the gene's LOEUF score, 0.92, which puts it in group 3 of 6, group 1 being the genes least tolerant of losing a copy. Missense variants: 365 observed, 423.36 expected, observed/expected ratio (o/e) 0.86, 90% interval 0.79 to 0.94. Synonymous variants: 180 observed, 182.63 expected, observed/expected ratio (o/e) 0.99, 90% interval 0.87 to 1.12.
Homologues: Orthologues: chimpanzee SLC51A (99% identical), macaque SLC51A (93% identical), rabbit SLC51A (87% identical), dog SLC51A (86% identical), pig SLC51A (83% identical), mouse Slc51a (82% identical), rat Slc51a (82% identical), guinea pig SLC51A (62% identical), tropical clawed frog slc51a (50% identical), Drosophila melanogaster Tmep (16% identical). Paralogues in human: TMEM184A (16% identical), TMEM184C (16% identical), TMEM184B (16% identical).
Diseases named in the same sentence as SLC51A in open-access papers:
SLC51A is named in the same sentence as 24 diseases in open-access papers, as found by Europe PMC text mining. Sharing a sentence is not in itself a finding about the gene and the disease. The quoted sentences say what the papers report.
cholestasis (12 papers, 2013 to 2024). Impairment of the bile flow caused by obstruction within the liver, or outside the liver in the bile duct system. "SLC51A also known as OSTalpha is widely expressed in the human small intestine and liver and is a major transporter of bile acids associated with cholestasis." (PMID 38992651, 2024). "Analysis of the transporter’s expression in CLCOs revealed that SLC51A/B and ABCC3 were down-regulated by CPZ treatment, which might contribute to CPZ induced cholestasis in cholangiocytes." (PMID 38475870, 2024).
vitamin deficiency (2 papers, 2022 to 2025). A disorder that is caused by the deficiency of a vitamin. "PFIC6 gene (SLC51A) malfunctioning in PFIC patients seems to be related to chronic malabsorptive diarrhoea, coagulopathy, fat malabsorption, severe fat-soluble vitamin deficiency, rickets, and mild liver involvement." (PMID 39984942, 2025).
Sepsis (1 paper, 2023). Sepsis is defined as life-threatening organ dysfunction caused by a dysregulated host response to infection. "CD177, ARG1, FAM20A, PCOLCE2, SLC51A, MMP9, were identified as most significantly upregulated in both SIRS and Sepsis on Day1, compared with healthy controls, with CD177 and ARG1 consistently higher for both SIRS and Sepsis at this and across all timepoints to discharge." (PMID 38332914, 2023).
steatosis (1 paper, 2021). Increased lipid within the cytoplasm of cells. "Some genes negatively associated with serum ferritin and steatosis degree, were consistently downregulated after treatment with iron or iron + palmitic acid (SLC51A, MTUS1)." (PMID 33962692, 2021).
tumor (4 papers, 2010 to 2025). "Analysis of publicly available scRNA-seq data from 12 patients with CCA (GSE151530) confirmed the almost complete absence of SLC51A (OST-α) expression in CCA cells and other cell types within the tumor." (PMID 40324694, 2025). "Interestingly, gene SLC51A was up-regulated, while gene SLC51B was about 2-fold down-regulated in EC versus control tissue from patient with FIGO stage IA, low-grade tumour and tumour with ≤50% invasion into myometrium, which may affect the levels of the active OST heterodimer." (PMID 33917029, 2021).
cancer (1 paper, 2021). A tumor composed of atypical neoplastic, often pleomorphic cells that invade other tissues. "Six additional genes (SLC10A6, SLC22A1, SLC51A, SLC51B, SLCO1C1, SLCO4C1) were included to finally examine the expression of 15 genes encoding E1-S transporters in the total of 36 pairs of cancer and adjacent control tissue." (PMID 33917029, 2021). "There are very limited data available about expression of SLC51B and SLC51A in cancer." (PMID 33917029, 2021).
SLC51A also shares sentences with these, for which no sentence is quoted: colon cancer (3 papers); gallstones (3); hepatoma (2); Obesity (2); age-related macular degeneration (1); coagulopathy (1); congenital disorder of glycosylation (1); E. coli infection (1); Glucose intolerance (1); hyperlipidemia (1); Insulin resistance (1); liver cirrhosis (1); liver disease (1); microcephaly (1); Pruritus (1); rickets (1); staphylococcus aureus infection (1); vitamin D deficiency (1).